TGFA (transforming growth factor alpha)
Diseases named in the same sentence as TGFA in open-access papers (continued):
Sharing a sentence is not in itself a finding about the gene and the disease.
tumor (continued). "We employed a set of partial differential equations to simulate the concentration changes of five extracellular chemical cues (glucose, oxygen, TGFα, VEGF and fibronectin) in the tumor micro-environmental scale." (PMID 22935054, 2012). "In summary, our present study suggests that TGFα, via ErbB receptors, promotes KGN GCT cell cycle progression, enhances tumor cell proliferation and facilitates GCT cell migration." (PMID 23155381, 2012). "Increased expression and release of TGFα leads to both increased EGFR and activation of the downstream signaling pathway, which, in turn, leads to both increased proliferation of tumor cells as well as other enhanced cytoprotective responses." (PMID 21255411, 2011). "For TGFA/EGFR, a significant direct and inverse correlation was observed in normal and tumor samples, respectively." (PMID 20877637, 2010). "In the clinical setting, it will be important to define tumours whose growth is dependent on the EGFR and which are being driven by activating ligands such as TGFα and EGF." (PMID 11875715, 2002). "YY1 promotes tumor angiogenesis by stabilizing the hypoxia-inducible factor-1α (HIF-1α) and activating angiogenic factors like vascular endothelial growth factor (VEGF) and transforming growth factor alpha (TGF-α)." (PMID 38893192, 2024). "In many other tumours, including gastric cancer and melanoma, TGFA expression is up‐regulated, and TGF‐EGFR signalling may promote tumour development through the autocrine growth factor pathway." (PMID 38152044, 2024). "MET, GPI, ANGPTL4, HSPA5, TGFA, MIF, and ARTN were significantly up-regulated in tumor samples." (PMID 36447119, 2023). "As we have shown by western blot, in trap mice are the levels of ERBB ligands TGFA and EGF only reduced and not deleted, but this seems to be sufficient enough to reduce tumor growth and does not cause side effects." (PMID 37341059, 2023). "To determine whether all tumor areas are accessible to intravenously administered vectors, we injected scAAV2.CMV.eGFP vectors into tumor-bearing TGFα/c-myc HCC mice and stained tumor sections for eGFP using an anti-eGFP antibody." (PMID 35053588, 2022). "By targeting transforming growth factor-alpha (TGF-α), tribbles pseudokinase 1 (TRIB1), CCND2, and high-mobility group AT-hook 2 (HMGA2) and Src, miR-203, miR-224, miR-154, and miR-1, respectively, counteract EMT, tumor progression and metastasis." (PMID 33805590, 2021). "HIF proteins induce the expression of several genes involved in tumor phenotypes, such as platelet-derived growth factor (PDGF), transforming growth factor alpha and beta (TGF-α, TGF-β), matrix metallopeptidase 1 (MMP1), C-X-C chemokine receptor type 4 (CXCR4)." (PMID 30708988, 2019). "Since enhanced TGFα and BTC levels in the BL-BC tissues could be due to tumor heterogeneity, we analyzed the NCBI GEO dataset on 51 human BC cell lines to exclude this possibility." (PMID 30034618, 2018). "In a group of patients with oropharyngeal cancer who underwent curative RT, the levels of the EGFR ligand TGFα assessed by IHC in pretreatment tumor biopsies was not a prognostic marker." (PMID 27556186, 2016). "Finally, the secreted TGFα activates the EGFR/Raf/MEK/ERK signalling pathway, enhancing tumor cell proliferation." (PMID 26300397, 2015). "Although it plays a significant role in tumor progression, the mechanism by which TGFα confers a growth advantage to tumor cells and that by which TGFα is activated in tumor cells are still not completely understood." (PMID 26300397, 2015). "On the contrary, in our experimental set up WA decreased EMT-related components of the TGF-β signaling pathway (TGFA, TGFBR2, CDH11), as well as TGM2, HIF1A, several TNFSF family members and ANGPTL2, which stimulate tumor promoting pro-inflammatory responses and a hypoxic microenvironment." (PMID 24498382, 2014).
tumor (continued). "Mohammad showed that gene losses of AMY2A, TGFA, and REG1B in uterine leiomyosarcoma may be responsible for secondary changes that affect the progression and proliferation of the tumor." (PMID 24743780, 2014). "We investigated thyroid hormones levels in menopausal BrC patients because of their lack of estrogen and verified the action of T3 on genes regulated by E2 (TGFA, TGFB1, and PGR) and T3 (TNFRSF9, BMP6, and THRA) in primary BrC tissues exhibiting the early stages of tumor progression." (PMID 24701358, 2014). "Activation of the EGFR signaling pathway results in increased tumor proliferation, angiogenesis, metastasis, and tumor invasiveness through the binding of a number of different ligands, including EGF-like molecules, transforming growth factor-α (TGFα), and neuregulins to the receptor’s ectodomain." (PMID 23824671, 2013). "The incidence of liver tumors was significantly increased in mice carrying the TGFα transgene, while dietary selenium and selenoprotein status did not affect tumor number and multiplicity." (PMID 23460847, 2013). "As a first step in this direction, here we expressed a chimeric granzyme B fusion protein in human NK cells that carries the peptide ligand TGFα for targeting to EGFR, and evaluated its effect on natural cytotoxicity and its cell killing activity towards EGFR-expressing tumor cells." (PMID 23573299, 2013). "The expression of EGFR -L858R or TGFα does not significantly promote tumor growth in untreated cells (expressing MET)." (PMID 20500904, 2010). "The results in this paper showed that human TGFα-derived TGFαL3 is capable of directing SAgs to tumours and exerting an inhibitory effect on tumour growth, which makes TGFαL3SEAD227A an attractive candidate for immunotherapy on EGFR-expressing tumours." (PMID 21176167, 2010). "However, tumors expressing EGFR-L858R or having the TGFα autocrine production were considerably resistant to MET silencing, as demonstrated by a complete rescue in tumor incidence." (PMID 20500904, 2010). "Therefore, cells with high expression of KK-LC-1 may inhibit the MAPK signaling pathway by downregulating TGFA and PDGFB, thus showing enhanced anti-tumor immune response." (PMID 38972967, 2024). "Recombinant bacteria derived from the attenuated Salmonella enterica serovar Gallinarum that constitutively expressed transforming growth factor α (TGFα) fused to a modified Pseudomonas exotoxin A (PE38) showed marked antitumor effects on tumor-bearing mice without any notable systemic toxicity." (PMID 36900277, 2023). "A study on exosome secretion from human keratinocytes found that induction of hypoxia and H2O2 (which induces inflammatory stress response) can make a variety of normal and tumor cell responses more dependent on the transforming growth factor-alpha (TGF-α) non-canonical pathway." (PMID 38203424, 2023). "In the paradigm of full differentiation and polarization by tumor cells alone, our results do not support a clear role for TGFα in polarization, as the primary effect of inhibiting TGFα is the loss of CD68+ macrophages rather than a shift in the percentage of CD163+ macrophages." (PMID 33069212, 2020). "Additionally, MET, TGFα, FGF2, CD151, and MMP3 are some of the oncogenic targets of miR-152 in human cancers; by targeting these genes, miR-152 leads to inhibition of cell proliferation and tumor metastasis." (PMID 33680048, 2020). "Moreover TGFα plasma levels were higher during treatment with cetuximab, even though they do not influence tumor response." (PMID 26318427, 2015). "This association may coincide with estrogenic response on gene expression and highlight the effect of TAM usage in hyperthyroid patients, especially considering the proliferative and apoptotic effects of TGFA and TGFB1, respectively, on the initial tumor progression stages." (PMID 24701358, 2014).
tumor (continued). "Thus the FGFR4 deficiency has no direct and significant effect on tumor-associated levels of the EGFR family members Her1 and 2, two of which likely underlie the TGFα-driven tumors." (PMID 24279986, 2013). "Moreover, human GCT cells express the ligand TGFα and its ErbB receptors suggesting that components are available in human GCTs to promote the proposed actions of TGFα on GCT cell proliferation and facilitate tumor cell migration in an autocrine and/or paracrine manner." (PMID 23155381, 2012). "Using two model systems we have shown that PCNA is induced in non-cycling cells by adjacent transplanted tumour cells and that this phenomenon may be mimicked by the in vivo administration of growth factors (transforming growth factor alpha and epidermal growth factor)." (PMID 7914422, 1994). "In conclusion, our data suggest that while necessary, NRG1 positivity alone does not fully predict KTN3379 anti-tumor activity, but its activity was enriched in cell lines that expressed both NRG1 and high levels of AREG or TGFα." (PMID 28723928, 2017). "In TGFα/cMyc mice, significantly upregulated TGF-β2 expression but no upregulation of TGF-β1 expression was observed in tumor tissue compared to normal tissue (paired samples)." (PMID 26799667, 2016). "Despite one simple HCA near a transplant tumor after TTx, neither the EGFR nor the TGFα were upregulated in hormonal induced alterations of hepatocytes after TTx." (PMID 27669229, 2016). "The few macrophages present in the TGFα-negative tumors in our study did not express VEGFC, but they did so when tumor cells were transfected with TGFα transgenes and then implanted into the cecal walls of mice." (PMID 23986907, 2013). "Importantly, in this latter study, Tspan6 was found to interact with TGFα via syntenin, and its absence led to increased TGFα release in EVs, making organoid growth independent of exogenous EGF and enhancing tumor formation in APC mutant animals." (PMID 40135387, 2025). "TGFA transcripts were significantly higher in PTC metastases when compared with normal thyroid samples, and although not significant, TGFA levels trended upwards with tumor stage." (PMID 20877637, 2010). "Indeed, we have established that these three inhibitors block the shedding of ADAM-17 targets such as TNFα, TGFα and amphiregulin (AREG) with the same efficacy (data not shown) whereas TMI-2 and TMI-005 only partially inhibit tumor cell growth and do not induce apoptosis." (PMID 23028451, 2012).
cancer (219 papers, 1989 to 2026). A tumor composed of atypical neoplastic, often pleomorphic cells that invade other tissues. "The TGFα-EGFR pathway in both cancer-associated endothelial cells and cancer cells themselves is essential in the development of colon cancer." (PMID 35402265, 2022). "Anomalous expression of TGFα or EGFR by cancer cells is associated with an aggressive phenotype and poor prognosis, also because the activation of EGFR signaling results in up-regulation of pro-angiogenic factors such as VEGF." (PMID 28906427, 2017). "This is unexpected although in many cancer cell lines with either endogenous or exogenously introduced K-ras mutation, production of erbB1 ligands, mainly TGFα and AREG, is up regulated." (PMID 23762292, 2013). "MiR-376c has been shown to regulate the expression of TGFA, therefore, the sensitivity of cancer cells to cisplatin chemotherapy may be associated with the miR-376c/TGFA pathway." (PMID 32020849, 2021). "Leucine-rich α2 glycoprotein (LRG1) has been identified as a marker of granulocyte differentiation, is involved in neovascularization by altering TGFα signaling at endothelial cells, and has recently been found elevated in plasma associated with distinct cancers including pancreatic." (PMID 30214418, 2018). "Previous studies have shown that TGFA is linked to ERBB signaling, cell survival, and growth, while Cx43 has been reported to inhibit cancer cell growth through cell-cell communication or protein-protein interactions." (PMID 40861849, 2025). "Several studies have shown that TGFA can improve cancer growth and progression, but data on its impact on the occurrence and advancement of CESC is limited." (PMID 38152044, 2024). "EGFR, the receptor of TGFα, is highly expressed in ESCA, which is known to be associated with the poor prognosis of a cancer." (PMID 39796131, 2024). "By applying the method outlined in Method 7, we have predicted BMP6, TGFα, and TGFβ1 as the growth signals specifically needed by the cancer type." (PMID 39796131, 2024). "Transforming growth factor alpha (TGFα) is a ligand for the EGF receptor and has been associated with many types of cancer." (PMID 36608258, 2023). "Previous studies have demonstrated that TGFα is a more potent agonist for EGFR than EGF in various biological systems, highlighting the significance of CAF-derived TGFα in regulating EGFR-mediated cancer cell chemoresistance." (PMID 37821657, 2023). "We show that treatment with cetuximab or TGFα depletion represses the promoting effect of rCAFs on chemoresistance in both cancer cell lines and patient derived organoids." (PMID 37821657, 2023). "Combined multi-omics and biochemical analyses indicate an elevated PI3K/AKT/p65 driven cell survival and cytokine production in rCAFs, while rCAF-secreted TGFα promotes cancer cell chemoresistance by activating EGFR/Src/STAT3 survival signaling axis." (PMID 37821657, 2023). "PE38, which lacks an intrinsic cell-binding domain, binds to EGFR-expressing cancer cells via the TGFα moiety in the recombinant toxin." (PMID 36900277, 2023). "This contributes to the increased CAF population in chemoresistant patient-derived tumors compared to chemosensitive patient-derived tumors and promotes cancer cell chemoresistance through TGFα-EGFR paracrine signaling." (PMID 37821657, 2023). "To examine the effect of TGFα expression on rCAF mediated cancer cell chemoresistance, we next transfected rCAFs with TGFα targeting siRNAs, while the knock-down effect of TGFα production was confirmed by western blot and RT-PCR analyses." (PMID 37821657, 2023). "Treatment with anti-EGFR cetuximab restores the chemosensitivity of tumors derived from co-injection of cancer cells and rCAFs in vivo, while the serum level of TGFα determines NACT response in HNSCC patients." (PMID 37821657, 2023). "Overall, our results indicate that rCAFs mediate cancer cell chemoresistance via the TGFα-EGFR paracrine signaling." (PMID 37821657, 2023).
cancer (continued). "Overall, our results suggest that p65 acts as an upstream regulator of TGFα secretion in rCAFs, thereby modulating the crosstalk between cancer cells and rCAFs." (PMID 37821657, 2023). "It is worth noting that in various biological systems, TGFα has been shown to be a more powerful agonist for EGFR than EGF23,24, indicating the potential importance of TGFα in regulating cancer progression." (PMID 37821657, 2023). "As a key molecule linking LINC00857 and TGFA, miR-340-5p has attracted extensive attentive in human cancer." (PMID 33661995, 2021). "PE38 binds to EGFR-expressing cancer cells due to the TGFα fragment present in the recombinant fusion protein." (PMID 33738260, 2021). "In contrast, our findings suggest that cancer cell-derived TGFα can directly support macrophage differentiation." (PMID 33069212, 2020). "EGFR is activated by binding EGF or transforming growth factor alpha (TGFα); this receptor-ligand binding leads to DNA synthesis, cell proliferation and cancer growth." (PMID 32942747, 2020). "In prior radiation oncology-based studies we have demonstrated that ionizing radiation, in carcinoma cells, causes two waves of ERBB1 and ERK1/2 activation, the second wave being caused by autocrine TGFα signaling." (PMID 32983965, 2020). "The next highly expressed gene Transforming Growth Factor-Alpha (TGFA) which stimulate angiogenesis in various tissue such as carcinoma." (PMID 32494757, 2019). "In turn CAF-derived TGFα induces epidermal growth factor (EGFR) signaling in cancer cells which stimulates cancer cell growth." (PMID 29854318, 2018). "PE38, which lacks an intrinsic cell-binding domain, binds to EGFR-expressing cancer cells via the TGFα moiety within the recombinant toxin." (PMID 28473665, 2017). "In cancer, EGFR is often mutated and, for this reason, continually activated and stimulated because of the sustained production of EGFR ligands such as EGF, TGFα, amphiregulina and heparin-binding EGF." (PMID 28906427, 2017). "EGFR ligands implicated in human cancers, include EGF, EREG, amphiregulin (AREG), heparin-bound EGF (HB-EGF) and transforming growth factor alpha (TGFα)." (PMID 26958807, 2016). "Studies investigating the signaling pathways that promote the growth and spread of cancer cells suggest that the information transmitted by means of TGFα-EGFR signaling is particularly important for progression of tumors that develop in the colon." (PMID 23986907, 2013). "In the pathways in cancer, TGFA and ERBB2 are both important regulators of normal mammary gland physiology, and aberrations in their signaling have been associated with breast tumorigenesis." (PMID 23369492, 2013). "As a cancer driver, we used TGFα, a transgene that leads to increased hepatocarcinogenesis in the later stages of life." (PMID 23460847, 2013). "Stat3 activity in these cancer cells has been shown to depend on autocrine activation of EGFR by secreted TGFα." (PMID 21264347, 2011). "The EGFR and its respective ligands such as TGFα trigger growth and prevent apoptosis by autocrine and/or paracrine mechanisms in many cancer cell lines." (PMID 11953870, 2002). "This study examined the expression of epidermal growth factor (EGF) cell-surface receptors, the response to exogenous ligand and the autocrine production of transforming growth factor alpha (TGF-alpha) in normal and carcinoma-derived human oral keratinocytes." (PMID 8286215, 1994). "Measurements of transforming growth factor alpha (TGF-alpha) in cancer patients have produced variable results." (PMID 2785399, 1989).